TK1 (thymidine kinase 1)
Diseases named in the same sentence as TK1 in open-access papers (continued):
Sharing a sentence is not in itself a finding about the gene and the disease.
cancer (continued). "In this study, we evaluated if feline serum TK1 could be used for discriminating cancer from other diseases and showed that felines with malignant diseases had significantly higher serum TK1 activity than those of healthy ones." (PMID 34579716, 2021). "TK1 is therefore a potential biomarker for cancer recurrence and treatment monitoring, and may also have advantages over current biomarkers." (PMID 35127491, 2021). "In cancer cells, TK1 is upregulated and the usual cell cycle regulated degradation during mitosis is disrupted and excess TK1 leaks out and it can be detected in serum from patients with malignant diseases and also in some cases of bacterial infection and/or inflammatory diseases." (PMID 34579716, 2021). "Whether this effect signifies its release from cancer cells due to chemotherapy, the role of TK1 as a metabolic marker of exposure of cancer cells to chemotherapy or of leukocyte recovery is unclear." (PMID 33714010, 2021). "TK1 has been identified in extracellular vesicles from numerous cancer types." (PMID 34442440, 2021). "In cancer cells TK1 is upregulated and excess TK1 is leaked into the blood." (PMID 34579716, 2021). "The serum level of TK1 has been found to correlate significantly with cancer stage." (PMID 35127491, 2021). "Similarly, [18F]FLT, commonly used to observe Thymidine Kinase 1 (TK1) activity, cannot be used specifically for immune cell imaging as other cancer cells with noticeable TK1 activity also demonstrate indistinguishable uptake." (PMID 33925941, 2021). "In cancer cells, TK1 is upregulated, resulting in leakage of excess TK1 into the blood." (PMID 34906077, 2021). "Therefore, serum TK1 has been used as biomarker for cancer diagnosis and prognosis in human medicine." (PMID 34579716, 2021). "Since the organ specificity of TK1 is low, effect of other cancers and non-specific causes (inflammatory or immunological) can also be studied." (PMID 33247667, 2020). "Additionally, they showed through the knockdown of TK1 that altered levels of GTP/GDP caused deregulation of Rho GTPase activity, leading to a reduction in cancer growth and progression in LUAD cell types." (PMID 33292474, 2020). "Overexpression of TK1 may not only be a byproduct of cancer cell processes, but part of selection processes that aid cancer cell progression." (PMID 33292474, 2020). "Thus, confirming previous reports of the membrane expression of TK1 and opening the door for additional studies exploring the targeting of TK1 in cancer cells." (PMID 32317865, 2020). "Broadening the spectrum of targetable TK1 specific epitopes could help us increase our ability to target TK1 in cancer patients." (PMID 32317865, 2020). "In addition, we have described the generation and characterization of a new panel of high-affinity TK1 monoclonal antibodies, targeting six different epitopes, for the detection and immunotargeting of cancer." (PMID 32317865, 2020). "Studying TK1 regulation through in vitro and bioinformatic analyses will be beneficial for identifying the mechanisms behind its dysregulation in cancer and potentially identifying therapeutic targets to inhibit cancer progression." (PMID 33292474, 2020). "The antibodies presented here had the ability to detect and quantify TK1 in the picomolar range and potentially could allow us to measure TK1 levels in cancer patients." (PMID 32317865, 2020). "Current studies are now identifying links between TK1 and cancer pathogenesis." (PMID 33292474, 2020). "This indicates that TK1 may contribute to ACC pathogenesis as well as pathogenesis in other cancer types." (PMID 33292474, 2020). "TK1 upregulation has been found to be an early event in cancer development." (PMID 33292474, 2020). "The mechanisms underlying the susceptibility or resistance of cancer cells to OTS-412 replication and cytotoxicity may involve other factors besides TK1 expression level." (PMID 31963415, 2020).
cancer (continued). "A review by Topolcan and Holubec explained that intracellular TK1 has and could be targeted in cancer treatment and that TK1 may influence cancer development." (PMID 33292474, 2020). "In addition, the potential of the anti TK1 antibodies for the targeting of malignant cells was tested by measuring the antibody-dependent cell-mediated cytotoxicity (ADCC) responses of mono nuclear cells (MNC) against high-level TK1-expressing cancer cells." (PMID 32317865, 2020). "More recent in vitro and bioinformatic studies aim to identify additional pathways where TK1 could influence cancer pathogenesis." (PMID 33292474, 2020). "Therefore, the characterization of novel TK1 protein–protein interactions on the membrane of cancer cells can possibly lead to the development of more specific targeted therapies." (PMID 32317865, 2020). "CCNB1, CKS2, MKI67, RRM2, TK1 and TOP2A were found with positive clinical correlation to GLEASON SCORE, and we could clearly identify the core factors as cancer risk factors, the expression level increased as Gleason score elevated." (PMID 32266115, 2020). "In addition, serum levels of TK1 have been shown to be tied to cancer stage, so that higher levels of TK1 indicate a more serious prognosis." (PMID 33292474, 2020). "TK1 might interact with P21 by combining with the C-terminal domain of P21, and promote the proliferation of cancer cells." (PMID 32064235, 2019). "The prognostic role of TK1 has been widely studied in the cancer studies." (PMID 32064235, 2019). "Based on our finding that the TK1 expression level correlates with sensitivity to FTD, we suggest that FTD/TPI might efficiently treat cancers with high TK1 expression." (PMID 31138881, 2019). "Here, we hypothesized that the TK1 knockdown-mediated inhibition of cancer growth and progression results from decreased pools of dTTP, which leads to an altered GTP/GDP ratio and the deregulation of Rho GTPase activity." (PMID 31589613, 2019). "TK1 was upregulated in carcinoma cells when compared to normal thyroid follicular epithelial cells." (PMID 32064235, 2019). "Comparing HER2 and TK1, both proteins are heterogeneously expressed in cancer tissues." (PMID 30214377, 2018). "This suggest that increased levels of TK1 may aid or have a function in invasion and migration potential in cancer cells." (PMID 30214377, 2018). "To more broadly evaluate relationships between [18F]-FLT-PET, TK1 levels and Ki67 immunoreactivity in common cell line xenograft models, we systematically evaluated these metrics using a colon-centric panel of human cancer cell lines." (PMID 23554961, 2013). "A proliferation marker such as TK1 could theoretically be used to distinguish between those cancers that proliferate slowly and more malignant forms that show rapid growth." (PMID 19396699, 2009). "Thus, the binding of Tunicamycin C resulted in TK1 inactivity, which could very likely halt cancer cell proliferation." (PMID 40699738, 2025). "Therefore, TK2 downregulation is a metabolic hallmark of pluripotency, whereas its maintenance in cancer cells is a consequence of TK1-driven nucleotide metabolism rather than a defining metabolic adaptation." (PMID 40571767, 2025). "In addition, an association between cancer stemness, poor prognosis of HCC and up-regulation of key enzymes of pyrimidine biosynthesis, such as deoxythymidylate kinase (DTYMK), thymidylate synthase (TYMS) and thymidine kinase 1 (TK1), has been described." (PMID 37108625, 2023). "Therefore, TK1 serum expression could potentially aid in identifying malignancies across multiple cancer types." (PMID 38033034, 2023). "Therefore, we speculate that TK1 may regulate PC activity by increasing its stability and enhancing superfluous metabolites and malignant proliferation of cancer cells." (PMID 35311151, 2022).
cancer (continued). "In addition, it is known that GDH participates in the Tricarboxylic acid (TCA) cycle, and it is possible that TK1 may regulate energy production through the TCA cycle to promote cancer progression." (PMID 35311151, 2022). "In addition to being a byproduct of cancer cell processes, overexpression of TK1 might also result from selection mechanisms that promote the growth of cancer cells." (PMID 36358602, 2022). "ROC analysis indicated that serum TK1 could serve as a promising cancer biomarker in horses." (PMID 34906077, 2021). "The mechanisms through which TK1 is expressed on the surface of cancer cells remains unknown." (PMID 32317865, 2020). "Thus, the combination of antibodies targeting multiple regions of the TK1 molecule could help us increase our ability to target TK1 in cancer cells." (PMID 32317865, 2020). "High levels of TK1 protein in cancer sera may potentially be utilized together with other pathological indicators such as biopsies, laboratory tests, and radiological imaging to determine cancer diagnosis and prognosis." (PMID 33292474, 2020). "Therefore, the immunotargeting of TK1 may be a feasible approach for the elimination of cancer cells." (PMID 32317865, 2020). "Our results show, however, that in a time frame in which the loss of TK1 does not affect cell proliferation, that the loss does result in decrease in cancer cell invasiveness, indicating an effect on metastatic attributes that can be separated from the primary effect on cell proliferation." (PMID 31589613, 2019). "Furthermore, although TK1-deficient cells play a key role in determining the importance of TK1 for FTD cytotoxicity, TK1-specific-deficient human cancer cell lines have not been established." (PMID 31138881, 2019). "Notably, because the overexpression of TK1 and its association with poor prognosis has been detected in the clinical samples from a number of other cancer types, we expect that similar studies will establish the role of TK1 as a general driver for cancer growth and metastasis." (PMID 31589613, 2019). "Cancers that highly express TK1 may be efficiently treated with FTD/TPI." (PMID 31138881, 2019). "Therefore, we hypothesized that TK1 knockdown-mediated reduction in cancer growth and progression results from the deregulation of Rho GTPase activity through an altered GTP/GDP ratio." (PMID 31589613, 2019). "Whereas serum TK1 activity is elevated in cancer patients compared with healthy individuals and prognostic in patients with breast and other cancers, in very few studies have researchers evaluated the utility of serum TK1 for monitoring responses to cancer therapy." (PMID 29162134, 2017). "These TK1 antibodies are the only TK1 antibodies available today with a sensitivity and specificity high enough to discriminate between, one the one hand, healthy people and people of non-malignant diseases, and on the other, people with pre-malignancies and malignancies." (PMID 22247653, 2011). "For the polar aqueous fraction, the hub proteins obtained by evaluating the overexpressed genes in the three types of cancer (BRCA, COAD, and LUAD) were TYMS, CDKN1, TOP2A, AURKA, and TK-1." (PMID 40430485, 2025). "Taking thymidine kinase 1 (TK1) as an example, elevated TK1 expression is an early event in tumorigenesis and correlated with poor prognosis in various types of cancers." (PMID 40942076, 2025). "Thus, low concentrations of TK1 may be released from sources other than cancer and still affect OS." (PMID 36982234, 2023). "The results of this study showed that TK1 was positively correlated with cell cycle- and proliferation-related pathways, such as MYC target and MTORCI signaling pathway, in multiple cancer types." (PMID 37767092, 2023). "TK1 is a nuclear/cytoplasmic protein so just like LDH, it can leak out of cancer cells when they die." (PMID 37377898, 2023).
cancer (continued). "The results specifically presented here demonstrate that the monoclonal canine TK1 ELISA may serve as an efficient tool to estimate the increased cell proliferation responsible for the aggressiveness and type of canine lymphoma, which can aid cancer management in veterinary medicine." (PMID 37808109, 2023). "As expected, we confirmed that TK1 was positively correlated with cell cycle- and proliferation-related pathways, such as MYC target and MTORCI signaling pathway, in multiple cancer types." (PMID 37767092, 2023). "Impressively, TK1, RRM2 and IMPDH1 were positively correlated with Myc/Myc signatures in multiple cancer types, whereas HSD17B6, PYGM and ACACB were negatively correlated with Myc/Myc signatures." (PMID 36629054, 2023). "However, new evidence has shown that TK1 may have an emerging role as a target for cancer therapy." (PMID 35239730, 2022). "The activity of both, cytosolic (TK1) and mitochondrial thymidine kinase (TK2), is upregulated by anti-cancer agents targeting thymidine synthase (TS) in the pyrimidine de novo synthesis pathways." (PMID 35203388, 2022). "As this study has shown, anti-TK1-sdAb-IgG1 antibodies are capable of targeting mTK1 on cancer cells and elicit an ADCC response by human MNCs against TK1 high-level expressing cancer cells building on previous findings." (PMID 35239730, 2022). "To test the effects of UBE2T, TK1, CXCL12, and KPNA2 on cancer cell invasion, we knocked down these genes in murine CAFs via siRNAs." (PMID 35884546, 2022). "TK1, TCN1, CAV1, and HS3ST2 play indispensable roles in survival predictions and pathogenesis of various cancers." (PMID 35898471, 2022). "To comprehensively understand these four lncRNAs (LINC01224, CASC9, LINC00346, and TRPM2-AS) and seven target mRNAs (CCNF, PKMYT1, GCH1, TK1, PSAT1, ADAM33, and DDX11), we performed genome instability, immune, cancer stemness, and drug sensitivity analysis." (PMID 34368141, 2021). "The nucleoside analogues tested in this study, AZT, TFT, and 5FdU, are activated by TK1 and used for the treatment of HIV, herpes simplex virus type 1 and 2 and vaccinia virus infection or cancers in humans." (PMID 34906077, 2021). "The network was identified using a systems biology approach and cancer signaling networks to identify five highly expressed and connected proteins: HSP90AB1, CSNK2B, TK1, YWAHB, and VIM." (PMID 33292474, 2020). "Since membrane expression of TK1 was detected with several of the anti-TK1 antibodies, we decided to test their potential to target TK1 and elicit an in vitro ADCC response against cancer cells." (PMID 32317865, 2020). "However, it remains unknown whether TK1 is essential for FTD incorporation into DNA and whether this event is affected by the expression level of TK1 because TK1-specific-deficient human cancer cell lines have not been established." (PMID 31138881, 2019). "We assessed TK1 surface localization by flow cytometry and confocal microscopy in lung (NCI-H460, A549), breast (MDA-MB-231, MCF7), and colorectal (HT-29, SW620) cancer cell lines." (PMID 30214377, 2018). "A search of these data (v.17) showed that the TK1, R2, and TYMS proteins are expressed at high or medium levels in 25, 79, and 83% of the 20 cancer types surveyed, respectively." (PMID 29018771, 2017). "All these results indicated that suppression of TYMP by shRNA is an effective approach to enhance the selective cytotoxicity of dT-QX on cancer cells with high levels of TYMP and TK1." (PMID 25881156, 2015). "High levels of thymidine kinase 1 (TK1) and thymidine phosphorylase (TYMP) are key molecular targets by thymidine therapeutics in cancer treatment." (PMID 25881156, 2015). "More importantly, our in vitro studies demonstrated that the suppression of TYMP by shRNA significantly enhanced the selectivity of thymidine analog dT-QX on cancer cells that have high levels of TYMP and TK1." (PMID 25881156, 2015).
cancer (continued). "Mechanistically, treatment downregulated key nucleotide biosynthesis genes (DHFR, TK1) and the glycolytic enzyme gene (ENO1), while upregulating the oxidative stress response gene SLC7A11 (18.32-fold), suggesting disruption of cancer metabolic pathways." (PMID 42074264, 2026). "Given the limited understanding of molecular drivers of metastasis in OSCC and the lack of specific studies addressing TK1’s function in this cancer type, our study aimed to fill this gap." (PMID 40564887, 2025). "Cisplatin treated on HT29 cells did not have several differently expressed proteins; TK1 was commonly upregulated in both cancers." (PMID 39061185, 2024). "hTK1-IgY-rmAb#5 showed a specific immune response with thymidine kinase 1 (TK1) in TK1-positive/negative cell lysates by Western blotting and immunohistochemistry (IHC) in normal and cancer tissues." (PMID 36969497, 2023). "Serum TK1 was more sensitive than CEA and AFP in discovering people with malignant tumors." (PMID 37373974, 2023). "This study also provides evidence that single domain antibodies or nanobodies can be used to target mTK1 on cancer cells, an antibody approach that has not been previously used for the targeting of TK1." (PMID 35239730, 2022). "In PCa cancer tissues, the DNA methylation level of TK1 was remarkably lower than that in non-tumorous samples." (PMID 36035114, 2022). "Taken together, these results suggested that β-carboline-3-carboxylic acid dimers could arrest the cell cycle by suppressing TK1, DBF4, CCNA2, CDK2, and PLK1, together with influencing some cancer-related pathways to inhibit MG-63." (PMID 36325324, 2022). "We find genes, such as TK1 in LUAD and ELAVL1 in BRCA, predicted in only one sample but known to have a role in respective cancer types." (PMID 35620468, 2022). "The binding of TK1 monoclonal antibodies to their corresponding TK1 epitopes was observed in all cancer cell models but not in normal lymphocytes suggesting the suitability of anti-TK1 antibodies as a highly specific targeting approach in malignant cells." (PMID 35203388, 2022). "Notably, previous studies revealed that IGF2BP1, acted as a m6A reader, played an oncogenic role in cancer cells, through stabilizing methylated mRNAs of oncogenic proteins, including FSCN1, TK1, MARCKSL1, and MYC." (PMID 33853613, 2021). "Based on our results, the serum assessment of TK-1 in these patients had no relevance for early detection of this cancer." (PMID 33375435, 2020). "The mechanism behind intracellular TK1 upregulation has not been identified nor has its links to cancer progression been fully explored." (PMID 33292474, 2020). "With validations of experiments and HCC patients in multiple cohorts, we provided lines of evidence that TK1, TYMS and DTYMK the catalytic RLEs in pyrimidine biosynthesis play critical roles in cancer stemness and serve as potential therapeutic targets in poorly-differentiated HCC." (PMID 29100421, 2017). "siRNA knockdown of TK1 and/or TS did not sensitize cancer cells to gemcitabine indicating that, among the 3 enzymes, only TK2 is a candidate therapeutic target for combination with gemcitabine." (PMID 26087398, 2015). "This is the first demonstration of a direct role for TK2 in gemcitabine resistance, or any independent role in cancer drug resistance, and further distinguishes TK2 function from that of other dTMP-producing enzymes [cytosolic TK1 and thymidylate synthase (TS)]." (PMID 26087398, 2015). "The key question would be whether TK1 and TYMP were involved in the cytotoxic action of dT-QX in cancer cells." (PMID 25881156, 2015). "The most significant and unexpected finding was that serum TK1 activity and TK1 protein did not clearly co-elute in any of the sera analyzed from patients with malignancies." (PMID 25881026, 2015). "Thus, dT-QX serves a chemical entity to investigate how TK1 and TYMP impact the activity in cancer cells." (PMID 25881156, 2015).